STOM (stomatin)
Diseases named in the same sentence as STOM in open-access papers (continued):
Sharing a sentence is not in itself a finding about the gene and the disease.
tauopathy (1 paper, 2023). Neurodegenerative disorders involving deposition of abnormal tau protein isoforms (tau proteins) in neurons and glial cells in the brain. "The emergence of two microtubule-associated membrane scaffold proteins, STOM and KANK2, as top prioritized potential therapeutic targets for PSP, a primary tauopathy characterized by microtubule-associated protein tau neuropathology, is noteworthy." (PMID 37919278, 2023).
thalassemia (1 paper, 2024). An inherited blood disorder characterized by a decreased synthesis of one of the polypeptide chains that form hemoglobin. "In our study, we found overexpression of the genes SLC4A1, ANK1, EPB41, EPB42, SPTA1, SPTB, and STOM, all of which are involved in maintaining erythrocyte structure and function, in patients with thalassemia and SCD." (PMID 39519257, 2024).
vitiligo (1 paper, 2024). Generalized well circumscribed patches of leukoderma that are generally distributed over symmetric body locations and is due to autoimmune destruction of melanocytes. "Regarding ECA25, six significant genomic regions were identified, although genes related to biological processes associated with vitiligo (TXN, LPAR1, SLC46A2, PRPF4, TRIM32, STOM, BRINP1, and DAB2IP) were only found in five of them." (PMID 39199954, 2024).
cancer (9 papers, 2014 to 2025). A tumor composed of atypical neoplastic, often pleomorphic cells that invade other tissues. "We previously showed that the expression of an integral membrane protein, called stomatin, was increased in cancer cells following their association with stromal cells." (PMID 39377541, 2024). "Although why stomatin down-regulation is associated with metastases in HER2-positive cancers remains uncertain, our results may suggest an interaction between HER2 receptor and stomatin in the lipid raft microdomains." (PMID 27577936, 2016). "To better understand the role of stomatin in different tumor types, we first conducted a pan-cancer analysis of the stomatin gene." (PMID 40485728, 2025). "Current research has identified abnormal stomatin expression in several types of malignant tumors; however, findings on its role remain inconsistent." (PMID 40485728, 2025). "In summary, these findings underscore the potential utility of stomatin as a prognostic marker across various cancer types." (PMID 40485728, 2025). "The ability to suppress cancer metastasis was shown for HTC116 line-specific EV protein stomatin (STOM)." (PMID 32916986, 2020). "Stomatin has been shown to have decreased expression in cancer cells." (PMID 27577936, 2016). "To confirm our findings, we checked the protein expressions of two of these genes—STOM and TGM2 in HeLa WT and KO cells due to their reported roles in promoting metastasis in different cancer entities." (PMID 36399280, 2022). "When distant metastases were defined as cancer recurrence for patients of stage I-III, stomatin was also an independent prognostic factor using multivariate analysis in this study." (PMID 27577936, 2016). "As there is a lack of data about stomatin participation in the main cancer-related signaling pathways, it was especially interesting to found out its association with positive lymph node metastasis status of patients with NSCLC." (PMID 24533441, 2014). "There was no statistical difference in patient age, cancer grade, cancer stage, and expression of estrogen receptor/progesterone receptor among women of positive stomatin expression compared with those of negative stomatin expression." (PMID 27577936, 2016).
tumor (7 papers, 2014 to 2025). "Finally, we investigated the specific effects of stomatin on tumor growth and progression, aiming to reveal the underlying regulatory mechanisms." (PMID 40485728, 2025). "After recombinantly expressing the first functional B-VIREM–derived antibody (Vab1) recently identified in a tumor-associated macrophage, we found that Vab1 specifically recognizes stomatin, a strictly intracellular membrane-associated autoantigen that is ubiquitously expressed." (PMID 37656789, 2023). "MR analysis establishes a positive causal relationship between stomatin and DLBCL, further corroborating the role of stomatin in tumor growth and progression." (PMID 40485728, 2025). "We also analyzed stomatin protein expression in orbital DLBCL tumor tissues and examined its relationship with pathological features." (PMID 40485728, 2025). "The goal of this study is to explore the specific expression pattern of stomatin in orbital DLBCL, particularly in comparison to other tumor types, where stomatin exhibits relatively higher expression levels." (PMID 40485728, 2025). "The results regarding cell proliferation, invasion, migration, and apoptosis indicated that stomatin enhances tumor cell progression." (PMID 40485728, 2025). "Among them, stomatin was highly expressed in tumor tissues, demonstrating a degree of specificity in DLBCL." (PMID 40485728, 2025). "For example, protein ERGIC-53 was overexpressed, while stomatin was underexpressed in all tumor regions compared to adjacent normal ones with fold-changes (FCs) of 1.5–2.2 and 0.26–0.38, respectively." (PMID 37069213, 2023). "Stomatin protein expression was decreased in 80% of tumor samples compared to corresponding normal tissue samples and its down-regulation was associated with positive lymph nodal status (p < 0,05, χ2-test)." (PMID 24533441, 2014). "As follows from the table, stomatin mRNA expression increased in the majority of the mesenchymal tumor specimens." (PMID 24533441, 2014). "These explanations are quite plausible, as we observed a significant decrease in both mRNA and protein expression levels of stomatin in the majority of tumor specimens." (PMID 24533441, 2014). "The results showed that the expression levels of stomatin vary across different tumor types." (PMID 40485728, 2025). "Second, we have only examined the expression of stomatin in orbital DLBCL tumor tissues." (PMID 40485728, 2025). "Stomatin could promote tumor progression and maybe stomatin is a good therapeutic target for orbital DLBCL." (PMID 40485728, 2025). "Additionally, stomatin impaired the Akt signaling pathway to suppress tumor growth." (PMID 39377541, 2024). "Bioinformatics analysis revealed that stomatin is overexpressed in DLBCL patients relative to healthy individuals, highlighting its role in tumor promotion." (PMID 40485728, 2025). "However, the functions and mechanisms of stomatin in tumor tissues remain unclear." (PMID 40485728, 2025). "Several of these EPINs have promoters of differentially expressed genes (such as DLL1, STOM and SEC11C in the GEPIA tumor/normal dataset; ID2, RPS27, SEC11C, CASZ1, CRTC2, C5 and STOM in the LNCaP/LHSAR dataset; see Methods, Differential Gene Expression)." (PMID 38057321, 2023). "The reduced clonogenic growth of MDA-MB-231 herein may be attributed to the upregulation of some tumor suppressor proteins such as TSPAN6, MAPK6, SPRY2, HAUS4, stomatin (STOM) and conserved oligomeric golgi complex subunit 8 (COG8)." (PMID 38283944, 2023).
infection (3 papers, 2009 to 2023). The state of being infected such as from the introduction of a foreign agent such as serum, vaccine, antigenic substance or organism. "In the future, further studies, e.g., involving infection of stomatin-deficient mice, would be highly interesting to prove the in vivo importance of stomatin in host-pathogen interactions." (PMID 36719247, 2023). "In line with this, by immunofluorescence we detected stomatin in the phagosomal membrane of RAW264.7 macrophages after infection with A. fumigatus conidia." (PMID 36719247, 2023).
adenocarcinoma (1 paper, 2014). A common cancer characterized by the presence of malignant glandular cells. "Here we present novel data on mRNA and protein expression of stomatin, flotillin-1 and −2 in human adenocarcinoma and squamous cell lung carcinoma specimens." (PMID 24533441, 2014).
STOM also shares sentences with these, for which no sentence is quoted: viral infection (2 papers); Cognitive impairment (1); COVID-19 (1); diffuse large B-cell lymphoma (1); dystonia 9 (1); metabolic syndrome (1); movement disorder (1); orbital (1); orbital tumor (1); Ovalocytosis (1); overhydrated hereditary stomatocytosis (1); progressive supranuclear palsy (1).